NR2E1 (nuclear receptor subfamily 2 group E member 1)
Description:
Orphan receptor that binds DNA as a monomer to hormone response elements (HRE) containing an extended core motif half-site sequence 5'-AAGGTCA-3' in which the 5' flanking nucleotides participate in determining receptor specificity (By similarity). May be required to pattern anterior brain differentiation. Involved in the regulation of retinal development and essential for vision. During retinogenesis, regulates PTEN-Cyclin D expression via binding to the promoter region of PTEN and suppressing its activity (By similarity). May be involved in retinoic acid receptor (RAR) regulation in retinal cells.
Synonyms: Tll; TLX; XTLL
Tractability: Small molecule: a high-quality ligand is known; it belongs to a druggable protein family. PROTAC: a small molecule that binds it is known.
Target class: Nuclear hormone receptor subfamily 2 group E; Transcription factor; Nuclear receptor; Nuclear hormone receptor subfamily 2 group E member 1; Nuclear hormone receptor subfamily 2
Gene: Protein-coding gene on chromosome 6 (108,166,022 to 108,188,805, forward strand). Ensembl gene ENSG00000112333.
Subcellular location: Nucleus
Subcellular location (Human Protein Atlas): Nuclear bodies
Pathways (Reactome):
Gene expression (Transcription): Nuclear Receptor transcription pathway
Signal Transduction: Regulation of PTEN gene transcription
Gene Ontology:
Molecular function: protein binding; sequence-specific double-stranded DNA binding; DNA-binding transcription factor activity, RNA polymerase II-specific; nuclear receptor activity; nuclear steroid receptor activity; RNA polymerase II cis-regulatory region sequence-specific DNA binding; DNA-binding transcription activator activity, RNA polymerase II-specific; DNA-binding transcription factor activity; DNA-binding transcription repressor activity, RNA polymerase II-specific; enzyme binding; histone deacetylase binding; sequence-specific DNA binding; zinc ion binding
Biological process: cell differentiation; negative regulation of transcription by RNA polymerase II; nervous system development; intracellular receptor signaling pathway; nuclear receptor-mediated steroid hormone signaling pathway; positive regulation of neural precursor cell proliferation; positive regulation of stem cell proliferation; positive regulation of transcription by RNA polymerase II; regulation of DNA-templated transcription
Cellular component: chromatin; nucleoplasm; nucleus
Genetic constraint (gnomAD): Loss-of-function variants: 5 observed, 39.3 expected, observed/expected ratio (o/e) 0.13, 90% interval 0.065 to 0.27. The upper end of that interval is the gene's LOEUF score, 0.27, which puts it in group 1 of 6, group 1 being the genes least tolerant of losing a copy. Missense variants: 270 observed, 471.72 expected, observed/expected ratio (o/e) 0.57, 90% interval 0.52 to 0.63. Synonymous variants: 184 observed, 189.54 expected, observed/expected ratio (o/e) 0.97, 90% interval 0.86 to 1.1.
Homologues: Orthologues: chimpanzee NR2E1 (100% identical), dog NR2E1 (99% identical), pig NR2E1 (99% identical), mouse Nr2e1 (99% identical), rat Nr2e1 (99% identical), macaque NR2E1 (98% identical), guinea pig NR2E1 (98% identical), rabbit NR2E1 (98% identical), tropical clawed frog nr2e1 (92% identical), zebrafish nr2e1 (91% identical), Drosophila melanogaster tll (44% identical), Caenorhabditis elegans nhr-69 (25% identical), and 21 more. Paralogues in human: NR2E3 (43% identical), NR2F1 (36% identical), NR2F6 (35% identical), NR2F2 (35% identical), RXRA (33% identical), NR2C2 (33% identical), RXRB (32% identical), RXRG (32% identical), NR2C1 (32% identical), HNF4A (31% identical), HNF4G (30% identical).